TIGIT (T cell immunoreceptor with Ig and ITIM domains)
Diseases named in the same sentence as TIGIT in open-access papers (continued):
Sharing a sentence is not in itself a finding about the gene and the disease.
melanoma (continued). "Conversely, TIGIT expression on tumor-Infiltrating Lymphocytes of melanoma patients or on peripheral blood T cells of gastric cancer patients was previously associated with poor outcomes." (PMID 35821240, 2022). "In mice and humans, including bladder cancer, melanoma, gastric cancer, colorectal cancer and other tumors, the expression of TIGIT on infiltrating CD8+ T cells is related to patient survival." (PMID 35433470, 2022). "Decreased levels of TIGIT were also observed on melanoma- or hepatocellular carcinoma-infiltrating NK cells when compared with circulating or peritumoral NK cells." (PMID 34503073, 2021). "The analyses of circulating ILC isolated from healthy donors and melanoma patients has further confirmed that CD56dim NK cells express TIGIT." (PMID 34885076, 2021). "In melanoma patients, circulating TIGIT+ NK cells exhibit lower killing activity against the CD155+ melanoma cell line FO-I despite harboring higher expression of granzymes A and B and perforin compared with TIGIT- NK cells." (PMID 34503073, 2021). "In melanoma patients, Tregs upregulate TIGIT expression and reduce the expression of CD226, which results in a decreased proliferation of effector T cells and DCs." (PMID 34806028, 2021). "Further, TIGIT blockade and rechallenge with melanoma resulted in potent antitumor memory response, possibly by the effect of NK cells enhancing CD8+ T cell immunity." (PMID 34199783, 2021). "Both melanoma and AML patients have an immunosuppressed microenvironment, largely due to low production of cytokines caused by high TIGIT expression." (PMID 34433460, 2021). "In this model we demonstrated that HLA-I APM upregulation by 3pRNA and anti-PD-1/anti-TIGIT antibodies synergistically enhanced the reactivity of CD8+ TILs towards autologous melanoma cells." (PMID 33554047, 2021). "The proportion of highly suppressive CD25hiFoxp3+Treg cells is increased in melanoma patients who present a high TIGIT/CD226 ratio in tumor-infiltrating Treg cells." (PMID 33670993, 2021). "Cancer testis antigen NY-ESO-1-specific CD8+T cell responses are increased by the addition of blocking mAbs against TIGIT and/or PD-1 when peripheral blood mononuclear cells (PBMCs) from melanoma patients are stimulated with NY-ESO-1157–165 peptide." (PMID 33670993, 2021). "In melanoma, a low TIGIT/DNAM-1 ratio in Tregs can attenuate their suppressive function and stability, resulting in a decreased number of Tregs in tumors." (PMID 34433460, 2021). "Dual blockade of TIGIT and PD-1 in melanoma patients synergistically increased the proliferation, degranulation, and cytokine secretion of tumor-infiltrating and tumor antigen-specific CD8+ T cells, demonstrating a potential for dual blockage." (PMID 32117298, 2020). "Enhanced in vivo anti-tumor activity and cytokine production was also found in human MART-1 TCR T cells expressing a CSR based on TIGIT (TIGIT:CD28) in a human melanoma xenograft mouse model." (PMID 32570906, 2020). "Double blockage of PD-1 and TIGIT in melanoma led to an increased proliferation and cytokine production of CD8+ TIL and was considered to be a promising approach in immunotherapy." (PMID 32235439, 2020). "Recently, the anti-TIGIT therapeutics have drawn great attention in treating colorectal cancer, breast cancer, and melanoma through modulating the activities of CD8+ T, T-reg, and NK cells." (PMID 33303760, 2020). "Combined blockade of PD-1/PD-L1 and TIGIT exhibited a more powerful anti-tumor effect in colon cancer, melanoma, and glioblastoma (GBM) compared with that of monotherapy." (PMID 32714324, 2020). "TIGIT is considered not to have any effectiveness against metastasis formation, as the number of lung nodules found was comparable in TIGIT−/− mice and wild-type mice after intravenous injection with B16 melanoma cells." (PMID 32117298, 2020).
melanoma (continued). "TIGIT expression has been reported on T cells isolated from tumor tissue of a variety of cancer types, including follicular lymphoma, multiple myeloma, melanoma, gastric cancer, NSCLC, and HNSCC, among others." (PMID 32508018, 2020). "TIGIT co-expression with PD-1 on CD8+ T cells was reported in melanoma and its elevated expression correlates with poor prognosis." (PMID 31554169, 2019). "Immune checkpoint blockade of T cell Ig and ITIM domain receptor (TIGIT) alone or combined with other immune checkpoint blockades moleculars has gained impressive results in the treatment of the melanoma and glioblastoma." (PMID 31090213, 2019). "Compared to the expression pattern of PD-1 on melanoma cells, TIGIT was intrinsically expressed on tumor cells in a broader range." (PMID 30555485, 2018). "IDO and prostaglandin E2 (PGE2) produced by melanoma cells act directly to inhibit NK cells while increased expression of ligands to regulatory receptors such as TIGIT modulate NK cell activity." (PMID 29276510, 2017). "Both studies showed that TIGIT can only regulate the function of melanoma-specific CD8+ T cells when it is coexpressed with PD-1." (PMID 29033936, 2017). "The synergism of TIGIT blockade in combination with PD-1 or PD-L1 blockade was further demonstrated in T cells from patients with advanced melanoma, where TIGIT was also found to be co-expressed with PD-1." (PMID 29211042, 2017). "We observed that melanoma cells and antigen presenting cells in metastatic melanoma express the PD-1, Tim-3 and TIGIT inhibitory ligands." (PMID 27461275, 2016). "Blockages of TIGIT and PD-1 synergize to improve T cell proliferation, cytokines production and degranulation in vivo in melanoma treatment and in vitro in HIV infection." (PMID 27415008, 2016). "This may be explained by the higher expression of TIGIT-compared to TIM3-specific ligands in the autologous patient-derived melanoma line used in this study." (PMID 41394272, 2025). "In this regard, improved cytokine production in ABE-TILs could be explained by the natural expression of TIM3 or TIGIT-specific ligands in melanoma tumor lines which can only suppress the Mock-EP TILs." (PMID 41394272, 2025). "originally found an upregulation of TIGIT and a co-expression of PD-1 in patients with melanoma." (PMID 39026970, 2024). "In addition, TIGIT expression is higher in CD8+ TILs than circulating CD8+ T cells in PBMCs in melanoma patients." (PMID 38893071, 2024). "Notably, TIGIT is found in various cancers, including melanoma, NSCLC, colon cancer, HCC, gastric cancer, glioblastoma, and hematological malignancies." (PMID 38375475, 2024). "Importantly, in one recent study of melanoma, it was shown that the TIGIT blockade primarily acts on NK cells to inhibit tumor growth, as NK-cell depletion resulted in an abrogation of the antitumor effects of the TIGIT blockade." (PMID 37444427, 2023). "Importantly, the CMC number correlated with CD8+TIGIT+ and CD8+TIGIT+TIM-3- cytotoxic T cell counts in the melanoma patient group." (PMID 36980196, 2023). "Both studies undermine the exceptional role of TIGIT+ Tc cells in uncontrolled tumor growth and spread, which may potentially explain our observation of a higher proportion of CD8+TIGIT-TIM-3− cells in melanoma patients vs. healthy individuals." (PMID 36980196, 2023). "In addition to PD1/PD-L1, CTLA-4, LAG-3, TIM-3, and TIGIT are potential melanoma checkpoints in the future." (PMID 37388230, 2023). "In addition, TIGIT modulate the suppressive activity of Tregs, thereby promoting tumor growth in B16F10 melanoma model mice, and these findings were further demonstrated in TIGIT knockout mice." (PMID 37670328, 2023). "We detected a melanoma cell-intrinsic TIGIT protein expression." (PMID 35410311, 2022). "Of note, we detected TIGIT protein expression in a number of melanoma cells." (PMID 35410311, 2022).
melanoma (continued). "The combined blockade of TIGIT and other new immune checkpoints may be a possible option for immunotherapy, especially in patients with gastroesophageal tumors and melanoma." (PMID 36211383, 2022). "Since we found significant correlations between TIGIT mRNA and methylation levels with known prognostic and predictive factors, i.e. immune cell infiltrates and IFN-γ signature, we performed survival analyses of melanoma patients stratified according to TIGIT mRNA and methylation levels." (PMID 35410311, 2022). "TIGIT is expressed on tumor cells, including lung cancer, colorectal cancer, melanoma and OC." (PMID 36497240, 2022). "Notably, very high frequencies of TILs expressing PD-1 and TIGIT have also been described in other cancers such as melanoma or head and neck squamous cell carcinoma." (PMID 36077799, 2022). "Finally, we investigated the clinical relevance of TIGIT methylation, mRNA expression, and TIGIT+ lymphocyte infiltration with regard to survival in melanoma patients." (PMID 35410311, 2022). "Therefore, in the present study we comprehensively analyzed TIGIT methylation in melanoma with regard to transcriptional activity, immune cell infiltrates, an IFN-γ signature, markers of T cell activation, patients’ prognosis, and response to immunotherapy." (PMID 35410311, 2022). "Curiously, in in vitro studies, IL-15 combined with TIGIT inhibition has also been found to increase the activity of NK cells’ cytotoxicity versus that of melanoma cells, and to reduce the development of tumor metastasis in mouse melanoma and soft tissue sarcoma models." (PMID 36231109, 2022). "TIGIT DNA methylation and expression may serve as predictive biomarkers in the context of immunotherapies in melanoma." (PMID 35410311, 2022). "In this study, we investigated a potential epigenetic regulation of TIGIT expression via DNA methylation and tested whether TIGIT gene methylation might serve as a feasible biomarker in melanoma." (PMID 35410311, 2022). "TIGIT overexpression has been found in the cellular microenvironment of several tumors, including lung, kidney, liver, glioma, melanoma, colorectal carcinomas, gastric cancer, and neuroblastomas." (PMID 35656508, 2022). "Moreover, an increased ratio of the TIGIT/DNAM-1 expression on tumor-infiltrating Tregs is related to a high percentage of Tregs in melanoma patients treated with mAbs targeted against PD-1 and/or CTLA-4." (PMID 36497240, 2022). "TIGIT is often co-expressed with PD-1 and other immune checkpoints on CD8+TILs.Dual PD-1/TIGIT blockers have achieved higher clinical efficacy in melanoma compared with single immune checkpoint inhibition confirming the potential possibility of TIGIT as an immunotherapy target." (PMID 36561512, 2022). "However, TIGIT protein expression did not correlate with CpG5 methylation, suggesting a more complex TIGIT regulation in melanoma cells compared to immune cells." (PMID 35410311, 2022). "IL15 stimulation with TIGIT blockades reverses altered CD155-mediated NK cell function in melanoma." (PMID 33810032, 2021). "To this end, we took advantage of an autologous melanoma model from a patient with primary ICB resistance, consisting of CD8+ tumor infiltrating lymphocytes (TILs) showing positivity for PD-1 and TIGIT, another inhibitory co-receptor, and melanoma cells expressing the corresponding receptor ligands." (PMID 33554047, 2021). "To date, tumour associated lymphocytes expressing TIGIT have been shown to exist in acute myeloid leukaemia, non-small cell lung cancer, colo-rectal carcinoma and melanoma." (PMID 33995362, 2021). "Furthermore, the dual blockade of the immune checkpoint axes of PD-1 and TIGIT has been superior in rejecting melanoma and non-small-cell lung carcinoma." (PMID 34638729, 2021).
melanoma (continued). "Data from other types of cancers with high incidence, such as prostate; breast; colorectal; urinary/bladder and skin cancers (melanoma); hematological cancers, such as non-Hodgkin lymphoma; and brain cancers, such as glioblastoma, are needed for anti-TIGIT antibodies." (PMID 34572463, 2021). "However, emerging studies have shown that inhibitory IC receptors PD-1, TIM-3, TIGIT and A2aR are also expressed on lung, melanoma, colorectal, cervical and gastric cancer cells." (PMID 33765543, 2021). "Notably, IL-15 can increase the expression of both CD226 and TIGIT by intra-tumoral NK cells, and combination therapy of IL-15 and TIGIT blockade increased cytotoxicity of NK cells against melanoma and suppressed lung metastasis in mouse melanoma models." (PMID 34367161, 2021). "In addition, for TIGIT/CD96 signaling pathway, most of the related genes were shown to have high expression levels in low risk melanoma patients." (PMID 34040608, 2021). "It has been reported that CD226 opposes TIGIT to disrupt Tregs in melanoma." (PMID 32983109, 2020). "Consistent with a previous study, a high TIGIT/DNAM-1 ratio in Tregs could also be found in melanoma patients, and this correlated with poor clinical outcome, which could promote Treg stability and its suppressive function." (PMID 32802845, 2020). "A costimulatory switch receptor that exploits TIGIT to the immune system's advantage was also recently investigated for efficacy in the context of ACT therapy against a xenograft model of established human melanoma." (PMID 32508018, 2020). "Consequently, in melanoma patients, co-blockade of PD-1 and TIGIT has been shown to improve proliferation, cytokine production and degranulation of CD8+ TILs." (PMID 33101304, 2020). "Furthermore, a study showed that TIGIT−/− mice intravenously injected with B16 melanoma cells had relatively few lung metastases and improved overall survival." (PMID 31681269, 2019). "TIGIT has been described as overexpressed in CD8 expressing TILs in melanoma." (PMID 28472085, 2017). "Additionally, TIGIT is co-expressed with PD-1 on activated CD8+ tumor-infiltrating lymphocytes from patients with melanoma." (PMID 27415008, 2016). "TIGIT expression on tumor-infiltrating lymphocytes (TILs) showed a significant correlation with PD-1 expression and was strongly associated with negative prognostic factors in melanoma." (PMID 40944710, 2025). "Evaluation of melanoma data from The Cancer Genome Atlas (TCGA) revealed strong positive correlations between PDPN expression and several immune checkpoint receptors, including PD-L1, CTLA4, LAG3, TIGIT, and BTLA, with the association with PD-L1 (CD274) being the most prominent (r=0.504, p<0.001)." (PMID 41573582, 2025). "Indeed, immune checkpoint molecules such as TIM3, LAG3 and TIGIT may also be epigenetically regulated and play a role in melanoma prognostication." (PMID 40307913, 2025). "Interestingly, while TIGIT+ NK cells demonstrated a higher lytic potential, they paradoxically exhibit lower actual lytic activity against CD155+ major histocompatibility complex (MHC)-class I deficient melanoma cells than their TIGIT- counterparts." (PMID 38229100, 2024). "Anti-TIGIT therapy alone could inhibited tumor growth only in the melanoma B16 F10 model." (PMID 35794399, 2023). "Upon binding to CD155, TIGIT also suppresses NK-mediated cytotoxicity and IFN-γ production, while blocking TIGIT/CD155 interaction effectively reverses NK cells’ dysfunction and confers anti-tumor activity, even in melanoma models refractory to melanoma-associated antigen specific CD8+T-cells." (PMID 37345056, 2023). "Furthermore, we validated the contribution of the TIGIT/CD155 axis to resistance in another large melanoma cohort, showing that the TIGIT/CD155 axis could induce inflamed resistance, including both primary and acquired resistance." (PMID 34795004, 2021).
melanoma (continued). "TIGIT is often coexpressed with PD-1; therefore, combination blockade of TIGIT and PD-1 could reverse functional exhaustion more effectively, as displayed in patients with advanced melanoma, who showed increased expansion and an elicited anti-tumor immune response." (PMID 32714324, 2020). "The Tian group has demonstrated that TIGIT is highly expressed on tumor-infiltrating NK cells and associated with NK cell exhaustion in different tumor models [CT26 colon cancer, 4T1 breast cancer, B16 melanoma, and fibrosarcoma induced by methylcholanthrene (MCA)] and patients with colon cancer." (PMID 31681269, 2019). "Simultaneous blocking of PD-L1 and TIGIT restored ex vivo effector T cell response in patients with advanced melanoma, and notably in chronic HIV infection, proposing TIGIT as a novel target for personalized therapy approach in PLHIV." (PMID 40868094, 2025). "Beyond PD-1/PD-L1 and CTLA-4, other checkpoints like TIM-3, TIGIT, and VISTA are co-expressed in melanoma TME, particularly on Tregs, marking them as potential targets." (PMID 40936894, 2025). "Mechanistically, melanoma cells upregulate alternative checkpoint receptors such as TIM−3, LAG−3, and TIGIT, which maintain T−cell exhaustion even after PD−1/PD−L1 or CTLA−4 blockade." (PMID 40936894, 2025). "The anti-PD1 therapy for melanoma offered better survival outcomes when the expression of PDCD1, TIGIT, and HAVCR2 was high." (PMID 40076932, 2025). "Combining anti-TIGIT and anti-LAG-3 with conventional anti-PD-1/anti-PD-L1 therapies has been shown to improve median survival in non-small cell lung carcinoma and melanoma." (PMID 40647508, 2025). "We found that expression of TIGIT was relatively high in clear cell RCC (ccRCC), but lower than in other malignancies, including melanoma, NSCLC, head and neck, and cervical cancer (Supplementary (Supp)." (PMID 39105820, 2024). "Given the high levels of TIGIT mRNA expression in melanoma, NSCLC, head and neck, and cervical cancer, we also stained TMAs containing these tumor types for CD3 and TIGIT." (PMID 39105820, 2024). "Melanoma patients with low KLK8 and high TIGIT were classified as the “Immune” subtype, a molecular subtype with favorable survival." (PMID 38273291, 2024). "Our study brings also pertinent information for the next generation of ICP receptors being harnessed in the clinic especially in melanoma, such as LAG3, TIM3 and TIGIT." (PMID 39687620, 2024). "We detected some level of TIGIT positivity in ~ 40% of RCC specimens, comparable to NSCLC, but lower than melanoma, head and neck, and cervical cancer cohorts." (PMID 39105820, 2024). "TIGIT, a complementary costimulatory receptor of DNAM-1, is expressed by NK cells and TILs in melanoma, capable of triggering immune suppressive responses." (PMID 38893071, 2024). "Several mAbs targeting TIGIT interaction with CD155 are currently in clinical trials and have displayed promising results in NSCLC, melanoma, and other solid tumors." (PMID 37629138, 2023). "Our research in melanoma-bearing Irf4GFP-DTR mice revealed a major subset of endogenous IRF4.GFP+ CD8+ TILs exhibiting high levels of PD-1, Tim-3, and TIGIT." (PMID 38178902, 2023). "Of note, GIMAP7 mRNA expression displays impressive correlations with immune checkpoints PDL2, CD96, TIGIT, BTLA, other immune checkpoints in melanoma, and across 30 cancer types." (PMID 36588164, 2023). "In melanoma, FAP+ CAFs induced TIGIT and BTLA expression on cytotoxic T lymphocytes via increased arginase activity." (PMID 37166418, 2023). "The cross-regulation we demonstrate between CD47 and other immune checkpoints we identified in melanomas supports further therapeutic trials combining CD47 blockades with ICIs targeting PD-1 and TIGIT." (PMID 36768931, 2023). "Consistent with these in vitro data, CD47 mRNA expression in TCGA melanomas had highly significant positive correlations with MCL1, CD40LG, TIGIT, and TNF mRNA expression." (PMID 36768931, 2023).